IRF8 (interferon regulatory factor 8)
Diseases named in the same sentence as IRF8 in open-access papers (continued):
Sharing a sentence is not in itself a finding about the gene and the disease.
tumor (continued). "Tumor-induced reductions in IRF8 also expand immature granulocytes that are known to have immune-suppressive functions and can otherwise promote tumor progression." (PMID 29593283, 2018). "Others have shown suppression of the transcription factor IRF8 during tumor progression expands the immature granulocyte and monocyte populations that are known to suppress anti-tumor immune responses." (PMID 29593283, 2018). "Further, we analyzed IRF8 target gene expression in GMPs, MDPs, and CDPs and found that, relative to controls, tumor-bearing mice had decreased mRNA expression of multiple MHC molecules, as well as TapBP, Tap2, Batf3, and Pml." (PMID 29593283, 2018). "To confirm that GCSF was upstream of IRF8 suppression, we measured IRF8 expression in cDC progenitors from tumor-bearing mice following GCSF neutralization." (PMID 29593283, 2018). "Increased expression of IRF8 was detected in DLBCL tumor tissues, which predicted worse DLBCL patient survival." (PMID 28537908, 2017). "The relative IOD of IRF8 and IRF8 mRNA levels were analyzed in paraffin-embedded tumor specimens from 48 DLBCL patients and in benign specimens from 18 controls." (PMID 28537908, 2017). "The present study provided novel evidence of decreased generation of Th17 cells and IL-17A and increased expression of IFN-γ and IRF8 in the DLBCL tumor microenvironment." (PMID 28537908, 2017). "The gene fusion between immunoglobulin heavy chain and IRF8 leads to the IRF8 overexpression in tumor lesions." (PMID 28537908, 2017). "Several studies have indicated that IRF8 acts as a functional tumor suppressor by inhibiting cell proliferation." (PMID 28388578, 2017). "DLBCL patients were separated into two groups according to the median relative IOD (3.75) of IRF8 in tumor tissues." (PMID 28537908, 2017). "Flow cytometry, immunohistochemistry, and quantitative real-time PCR were used to detect the distribution of Th17 cells and related cytokines and IRF8 in tumor tissues from DLBCL patients." (PMID 28537908, 2017). "In summary, our results show that increased expression of IRF8 inhibits the Th17 cells differentiation in the tumor environment of DLBCL patients." (PMID 28537908, 2017). "The importance of IRF-8 in regulating MDSC expansion during tumorigenesis is supported by the finding that tumor growth occurs more rapidly in Irf8-/- than B6 mice." (PMID 28968468, 2017). "Compared with the control (pcDNA3.1) group (n = 6), tumor volume and tumor weight were suppressed in the IRF8-expression group (n = 6), accompanied by inhibition of proliferation-related Ki-67 antigen." (PMID 28388578, 2017). "We further tested the anti-proliferation effect of IRF8 in vivo, in tumor-bearing nude mice with MDA-MB-231 xenografts." (PMID 28388578, 2017). "These conclusions are in agreement with a pro-tumor effect of IRF8, and this notion was supported by our present results." (PMID 28537908, 2017). "Our results showed that high levels of IRF8 in tumor cells inhibited the generation of Th17 cells and predicted unfavorable clinical outcomes in DLBCL patients." (PMID 28537908, 2017). "Sh-control-Th9 cells differentiated in the presence of IL-1β harboured a strong anti-tumour effect, which was completely lost when cells were infected with Sh-Irf8." (PMID 29233972, 2017). "In the present study, we found that DLBCL patients with higher levels of IRF8 in the tumor microenvironment had significantly worse disease-free survival and overall survival." (PMID 28537908, 2017). "Knockout of IRF8 was shown to suppress tumor growth in vivo and DLBCL cell proliferation in vitro by inhibiting p38 and ERK activation." (PMID 28537908, 2017). "Xenografts in irf8−/− zebrafish highlighted a strong impact of microglia on tumor progression for U87 cells and U251 cells." (PMID 27779463, 2016). "Altogether, these data indicated that IRF8 influenced tumor growth in part through negatively regulating MMP3 expression/function." (PMID 26008967, 2015).
tumor (continued). "In those studies, we made use of the mouse CMS4 tumor model, which enabled us to experimentally manipulate endogenous IRF8 levels by RNA interference." (PMID 26008967, 2015). "Knockdown of basal IRF8 levels in tumor cells was accompanied by enhanced MMP3 expression, while the converse held true when IRF8 was overexpressed." (PMID 26008967, 2015). "In another study, it was revealed that exogenous expression of IRF8 in a metastatic colon cell line restored, at least partially, the sensitivity of the tumor cells to Fas-mediated apoptosis." (PMID 25120651, 2014). "According to the cut-off value obtained from primary tumor sample analysis, IRF8 hypermethylation was present in 10/13 cell lines." (PMID 25120651, 2014). "Tumor tissues demonstrated significantly higher levels of IRF8 methylation (mean ± standard deviation, 11.6±10.3%) than matched non-malignant lung tissues (6.5±1.4%; Wilcoxon signed-rank test, P<0.0001)." (PMID 25120651, 2014). "IRF4 is an oncoprotein with anti-apoptotic properties and IRF8 functions as a regulator of apoptosis and tumor suppressor in many hematopoietic malignancies." (PMID 23658517, 2013). "IRF8 was also identified as a functional tumor suppressor, which is frequently silenced by epigenetic mechanism in multiple carcinomas." (PMID 24709797, 2013). "We show that IRF4 is stabilized by EBNA3C, which resulted in downregulation of IRF8 through proteasome-mediated degradation and subsequent inhibition of its tumor suppressive activity." (PMID 23658517, 2013). "The effects of two HDACi on IRF-8 expression in tumor cells were studied in vitro: TSA, a well-studied experimental pan-HDACi and DP, which is currently being tested in cancer clinical trials." (PMID 23028998, 2012). "Here, we employed this subline to further explore the relationship between tumor phenotype and IRF-8 responsiveness, but this time in response to HDACi." (PMID 23028998, 2012). "Nonetheless, the induction of IRF-8, in turn, modulates tumor response to immune attack via Fas-mediated apoptosis." (PMID 23028998, 2012). "Previously, we showed that IRF-8 expression in the CMS4 tumor model is required for Fas-mediated death, particularly in response to IFN-γ sensitization." (PMID 23028998, 2012). "Nonetheless, it is important to emphasize that tumor-cell expression of IRF-8 was crucial for therapeutic response to HDACi." (PMID 23028998, 2012). "Overall, our data show that HDACi enhances IRF-8 expression in tumor cells involving STAT1, and promotes Fas-mediated killing and antitumor activity via an IRF8-dependent pathway." (PMID 23028998, 2012). "Together, these results indicate that HDACi promote Fas-mediated tumor cell death, in part, through IRF-8-dependent pathways." (PMID 23028998, 2012). "Several studies now demonstrate that IRF-8 expression in various human cancers and tumor cell lines can be down-regulated by epigenetic mechanisms." (PMID 23028998, 2012). "Overall, our data are consistent with a model that tumor-cell expression of IRF-8 is integral for HDACi-induced antitumor activities." (PMID 23028998, 2012). "We further observed that low levels of both Fas and IRF-8 expression by tumor cells correlated with more rapid tumor growth." (PMID 23028998, 2012). "We showed that TSA treatment of mice bearing IRF8-competent tumor cells led to dramatic tumor growth inhibition, suggesting that this TSA-based schema can indeed facilitate antitumor activity in vivo." (PMID 23028998, 2012). "Methylation of SFRP1, IRF8, APC and RASSF1A were significantly associated with increased tumor grade and stage in samples from Taiwan." (PMID 21599969, 2011). "Regarding the samples from Taiwan, methylation of SFRP1, IRF8, APC and RASSF1A were significantly associated with increased tumor grade, stage." (PMID 21599969, 2011).
tumor (continued). "Further, it is also known that the IRF-8 gene is frequently epigenetically silenced in a number of tumours and that DNMTi can increase tumour cell sensitivity to apoptosis through upregulation of IRF-8." (PMID 22015556, 2011). "RAM+ cells were governed by ZFP42 and IRF8 maintaining anti-tumor immunity, while RAM- cells controlled by ILF2 and ISL1 promoted metastasis and immune evasion, with RAM- malignant cells enriched in patients over 65 years and associated with immunotherapy resistance." (PMID 42304383, 2026). "Apoptosis and immunological responses are controlled by the IRF (Interferon Regulatory Factors) family and members such as IRF1 and IRF8 are crucial for anti-tumor immunity because they activate T cells and dendritic cells, promoting the release of pro-inflammatory cytokines." (PMID 41155227, 2025). "However, despite its presence in tumor cells, the role of IRF-8 in the tumorigenic properties of cancer cells remains largely unexplored." (PMID 41315179, 2025). "Moreover, their expression of IRF8 links their transcriptional re-programming to anti-tumor Th1 activity." (PMID 40164596, 2025). "Notably, TAM-specific IRF8 deletion prevented exhaustion of cancer cell-reactive CTLs and suppressed tumor growth." (PMID 40083710, 2025). "Notably, IRF8-transduced tumor cells significantly reduce CCL2 secretion, resulting in decreased recruitment of myeloid cells into tumors via the CCL2–CCR2 axis." (PMID 41368628, 2025). "Irf8 is an immunomodulatory gene that regulates immune responses, inflammation, and tumor immunity." (PMID 40872627, 2025). "Notably, the combination of IRF8 overexpression and anti-PD-1 therapy significantly inhibited tumor growth in syngeneic mouse models." (PMID 39940857, 2025). "The degradation of IRF-8 ultimately contributes to tumor progression enhancement." (PMID 41315179, 2025). "It found that tumor-associated macrophages had upregulated genes regulated by IRF2, IRF7, IRF9, and STAT2, and downregulated genes regulated by Fos/Jun and IRF8, revealing decreased inflammatory response, TNF-α-induced proliferation, and reactive oxygen species production pathways." (PMID 39034998, 2024). "These evidences illustrate that IRF1, IRF4, IRF5, IRF6, and IRF8 may be candidate tumor-suppressors in CRC." (PMID 39384770, 2024). "This is required for the TAM ability to present cancer cell antigens, indicating that IRF8 may play a role in promoting tumour growth." (PMID 38792023, 2024). "Specific deletion of IRF8 in TAMs blocks T-cell exhaustion and inhibits tumor growth." (PMID 39372416, 2024). "Tumor cells will induce the expansion of TAMs, which requires TAMs to express IRF8." (PMID 39372416, 2024). "Moreover, Irf8+32−/− mice were protected against B16F10 tumor metastasis in the lungs, similar to C57BL/6 mice." (PMID 39559560, 2024). "In addition, the inhibition of IRF4, IRF5, IRF7, and IRF8 decreases the survival of PC patients, indicating these IRFs probably act as anti-tumor factors in PC." (PMID 39384770, 2024). "We therefore hypothesized that restoring IRF8 expression to tumor cells should sensitize the tumor cell to ferroptosis to suppress tumor growth in vivo." (PMID 36672246, 2023). "Conditional ablation of either SHP-2 or PD-1 in myeloid cells resulted in augmented phosphorylation of HOXA10 and IRF8 in vitro and enhanced differentiation, activation, phagocytosis and inflammatory responses in myeloid cells of tumor-bearing mice, leading to diminished tumor growth." (PMID 36581713, 2023). "However, knocking out IRF8 significantly decreased the tumor cell sensitivity to ferroptosis induction by RSL3." (PMID 36672246, 2023).
tumor (continued). "Previous studies found that ID1 is upregulated by some tumor-derived factors, such as transforming growth factor beta (TGFβ), in bone marrow-derived myeloid cells to promote the myeloid cell differentiation switch from dendritic cells (DCs) to MDSCs via downregulating Irf8 during tumor progression." (PMID 37996458, 2023). "Furthermore, overexpression of IRF8 in vivo in AML xenograft models resulted in decreased tumor volume, indicating the potential of IRF8 as a potential therapeutic target." (PMID 36969082, 2023). "In the tumor context, the production of prostaglandin E2 (PGE2) by tumor cells leads to cDC1 dysfunctionality marked by the downregulation of IRF8, and key effector cytokines such as CXCL9 and IL-12, resulting in poor CD8+ T cell tumor infiltration and ultimately in tumor immune evasion." (PMID 37520521, 2023). "In contrast, the MC011 IRF8.KO tumor grew constantly and rapidly in the immune-competent mice." (PMID 36672246, 2023). "IRF8 is often silenced in tumor cells by DNA hypermethylation at its promoter." (PMID 36672246, 2023). "Furthermore, IRF8.KO tumor cells grew significantly faster than WT tumor cells in immune-competent mice." (PMID 36672246, 2023). "However, the function of the CTL-IFNγ-activated IRF8 pathway in tumor cell ferroptosis requires further study." (PMID 36672246, 2023). "In this study, we identified IRF8 as a ferroptosis regulator in tumor cells." (PMID 36672246, 2023). "In fact, one candidate identified in this analysis as a potential RIDD substrate is the ER-resident FC receptor Like A (Fcrla), which has been previously identified as part of a BATF3/IRF8 transcriptional program that confers tumor immunogenicity in cDC1s independently of cross-presentation." (PMID 37346037, 2023). "Human tumor cells may use the IRF8 promoter DNA methylation as a mechanism to repress IRF8 expression to advance cancer through acquiring apoptosis resistance and OPN up-regulation." (PMID 36078039, 2022). "Furthermore, IRF8 has been found to protect against immune evasion of tumor cells via the IRF8-OPN axis to control tumorigenesis and progression." (PMID 36078039, 2022). "IRF8 is an interferon regulatory factor with tumor suppressive function." (PMID 35610556, 2022). "In tumor-bearing mice, IRF8 expression level is silenced in both PMN-MDSCs and M-MDSCs." (PMID 36078039, 2022). "Conversely, CD206 and IRF8 were detected in fewer cells in the tumor microenvironment." (PMID 36230752, 2022). "Furthermore, we analyzed the correlation between IRF8 expression and clinic pathological characteristics of TCGA‐LIHC samples in the UALCAN database and found that the IRF8 transcription was negatively correlated with higher tumor stages and grades." (PMID 35845349, 2022). "IRF8 suppresses inflammation and is involved in tumor formation." (PMID 36078039, 2022). "In contrast, in irf8−/− mutants, AsPC1 showed a significant 50% decrease of the tumor size." (PMID 35742884, 2022). "In the TME, interferon regulatory factor 8 (IRF8)-dependent CD103+ cDC1 (CD141+ cDC1 in human) are the only APCs that can cross present tumor rejection Ags for activation of specific CTLs 23, which are sparsely distributed and frequently threatened by the hostile immunosuppressive environment." (PMID 35966588, 2022). "XCL1 forms a connection with tumor suppressors: IRF8 and ITK in early cancer stages." (PMID 35610556, 2022). "IRF8, a tumor suppressor, is also a potential therapeutic option to overcome tumor drug resistance." (PMID 35127830, 2022).
tumor (continued). "Interestingly, these data were substantiated by the identification of a unique cluster of neutrophil precursors that were expanded in tumour-bearing mice that expressed low levels of IRF8." (PMID 34685679, 2021). "To determine whether IRF8 could act as a biomarker that accurately stratifies patients for prognosis and potential response to therapies, we investigated whether tumor IRF8 expression correlated with improved outcome in distinct BC molecular subtypes." (PMID 33766090, 2021). "Besides these already known factors involved in AML progression, we also identified several novel candidates, including the interferon regulatory factor 8 (IRF8, also ICSBP), which has been described as a tumor suppressor in several other cancer types before." (PMID 33673123, 2021). "Since high IRF8 expression levels are correlated with improved outcome in HER2+ and TNBC subtypes, we evaluated whether tumor cell IRF8 expression correlated with the complexity or contexture of tumor-infiltrating immune cells." (PMID 33766090, 2021). "Consistently with in vivo findings, this suggests IRF-8 inhibits tumour cell invasion." (PMID 34085677, 2021). "Together, this implies that CD40L-CAR T cells affect the intratumoral cDC1/cDC2 ratio by stimulating CD11b−CD103− DN cell proliferation, upregulation of the cDC1-skewing IRF8 transcription factor, and, consequently, differentiation of DN cDCs to cDC1s in the tumor tissue." (PMID 33268774, 2020). "Our results here show a novel mechanism for IRF8-mediated tumor CD8+ T cell activation." (PMID 32039830, 2020). "Further, it has been hypothesized that tumor-induced IRF8 downregulation occurred through a STAT3-dependent interaction." (PMID 32849585, 2020). "GC patients with low expression of IRF8 in blood CD8+ T cells had a more advanced tumor stage." (PMID 32039830, 2020). "The majority of the CD68+IRF8+ TAMs (78%) were within 20 μm of tumor cells." (PMID 31477692, 2019). "Reduced IRF8 expression in the tumor as a marker of cDC1s is correlated with worse patient outcome." (PMID 29593283, 2018). "Irf8 levels are decreased in MDSC recovered from tumor-bearing mice and cancer patients." (PMID 28968468, 2017). "To determinate whether IRF8 could impair the anti-tumour functions of Th9 cells differentiated with IL-1β, we used the same strategy." (PMID 29233972, 2017). "Secondly, IRF8 upregulation was detected in DLBCL tumor tissues." (PMID 28537908, 2017). "Here, we investigated whether different levels of expression of IRF8 in tumor tissues could affect the survival of patients with DLBCL." (PMID 28537908, 2017). "In these models, we observed that Il9 mRNA expression and IL-9 protein secretion were reduced in tumour-infiltrating CD4+ T cells (TILs) or in CD4+ T cells from tumour-draining lymph nodes (TDLN) of Irf8f/fCd4cre mice compared to those of WT or Irf8+/+Cd4cre mice." (PMID 29233972, 2017). "IRF8 was expressed at various levels in the nuclei of tumor cells or TILs." (PMID 28537908, 2017). "In addition, we found that a high level of IRF8 in the DLBCL tumor microenvironment was a predictor of poor survival in DLBCL patients." (PMID 28537908, 2017). "In contrast, Th9 OT-II cells infected with Irf8 shRNA had a reduced anti-tumour effect." (PMID 29233972, 2017). "To determine whether IRF8 affects Th17 cells generation in the tumor microenvironment, we investigated IRF8 expression in tumor tissues and benign tissues by IHC and quantitative real-time PCR (qPCR), respectively." (PMID 28537908, 2017). "Furthermore, disruption of IRF8 function reduced tumor cell sensitivity to apoptosis and increased their metastatic potential, indicating its role as a TSG in multiple cancers." (PMID 28388578, 2017).